EGFR (epidermal growth factor receptor)
Diseases named in the same sentence as EGFR in open-access papers (continued):
Sharing a sentence is not in itself a finding about the gene and the disease.
soft tissue sarcoma (16 papers, 2007 to 2025). A malignant neoplasm arising from muscle tissue, adipose tissue, blood vessels, fibrous tissue, or other supportive tissues excluding the bones. "The tumor was stained with hematoxylin-eosin staining and IHC postoperatively, and the fluorescent tissue was confirmed to be soft tissue sarcoma, and the fluorescence signal was highly associated with the expression of EGFR." (PMID 35860548, 2022). "ABY-029 is an anti-EGFR affibody (<5% mass of antibody) linked to IRDye 800cw that has been explored in soft tissue sarcomas as 70% of these lesions exhibit EGFR expression." (PMID 34002555, 2021). "In 2005, high levels of EGFR expression in 281 patients with soft tissue sarcomas other than DFSP were significantly associated with the histological grade and with a shorter overall survival." (PMID 29492209, 2018). "EGFR expression has been documented in canine soft tissue sarcomas (STS), and the pharmacokinetics of gefitinib were also previously characterized in canine, supporting the feasibility of a relevant and comparative therapeutic study in this species." (PMID 41375061, 2025). "EGFR is highly expressed in bone and soft tissue sarcoma and is involved in osteolytic metastases of bone tumors." (PMID 35860548, 2022). "Promising biomarkers in common and aggressive STS subtypes are TEM1 for myxofibrosarcoma, TEM1, and PDGFRα for undifferentiated soft tissue sarcoma and EGFR for synovial sarcoma." (PMID 33535618, 2021). "Dr. Henderson from Geisel School of Medicine at Dartmouth presented his discussion on EGFR-based affibody tracers in orthopedic oncology, particularly in the management of soft-tissue sarcomas." (PMID 34002555, 2021). "Previous studies have shown that total epidermal growth factor receptor (EGFR) protein is highly expressed in soft tissue sarcoma (STS)." (PMID 28556791, 2017). "Although epidermal growth factor receptor (EGFR) is often over-expressed in soft tissue sarcoma (STS), a phase II trial using an EGFR inhibitor gefitinib showed a low response rate." (PMID 26909593, 2016). "Reviews show that osteosarcoma and soft tissue sarcoma can overexpress EGFR." (PMID 35860548, 2022). "Approximately 60% to 70% of soft-tissue sarcomas overexpress EGFR." (PMID 34002555, 2021). "EGFR amplification is found only in 3.5 to 7% of soft-tissue sarcomas." (PMID 29492209, 2018). "In other soft-tissue sarcomas, EGFR is activated through phosphorylation." (PMID 29492209, 2018). "In our 22 cases, as in 275 soft-tissue sarcomas reported elsewhere, EGFR expression was not linked to EGFR activating mutation, or to EGFR gene copy-number alteration." (PMID 29492209, 2018). "The blockade of EGFR as an important therapeutical intervention alone and in combination with chemotherapy has already been investigated in soft tissue sarcomas (including uterine leiomyosarcomas) using in vitro and in vivo (animal model) experiments with promising results." (PMID 23449029, 2013). "Finally, overexpression of EGFR protein was also demonstrated for soft tissue sarcoma." (PMID 30513863, 2018). "Notably, TEM1, VEGFR-1, EGFR, VEGFR-2, IGF-1R, PDGFRα, and CD40 are highly expressed in the tumor cells of soft tissue sarcoma." (PMID 40258773, 2025).
acute lymphoblastic leukemia (15 papers, 2010 to 2024). Leukemia with an acute onset, characterized by the presence of lymphoblasts in the bone marrow and the peripheral blood. "Two publicly available datasets (GSE231310 and GSE160311) revealed the elevated CD39 levels in CD19 CAR-T cells cocultured with the CD19+ acute lymphocytic leukemia cell line Nalm6 and in anti-EGFR CAR-T cells cocultured with EGFR+ A549 cells." (PMID 39431011, 2024). "Overexpression or EGFR-activating mutations are closely related to the development and proliferation of many types of cancers, especially human leukemia, such as acute myeloid leukemia and acute lymphoblastic leukemia (ALL)." (PMID 33562835, 2021). "miR- 101 has been described to be a pro-apoptotic factor in childhood acute lymphoblastic leukemia and miR-7 as an tumor suppressor inhibiting various receptor tyrosine kinases such as EGFR, IGF-1R and p21 activated kinase (PAK1)." (PMID 27542283, 2016). "While no other malignancy fits this model quite as well as CML, there are similar resistance mutation phenomena in Gastrointestinal stromal tumour (GIST), Ph + acute lymphoblastic leukaemia (ALL), EGFR-mutant non small cell lung cancer (NSCLC), ALK-rearranged NSCLC, and other cancers." (PMID 31138173, 2019).
anal carcinoma (15 papers, 2010 to 2024). "A high surface expression of Epidermal Growth Factor Receptor (EGFR) and low rates of EGFR and k-ras mutations seem to enable the use of cetuximab for anal cancer treatment, but only a couple of studies describe a small benefit regarding palliative treatment of anal cancer patients." (PMID 24886574, 2014). "Detection of overexpression of the epidermal growth factor receptor (EGFR) in anal carcinoma suggests a potential benefit from anti-EGFR therapies such as cetuximab." (PMID 39211371, 2024). "Prior trials in this setting have demonstrated no improvement in clinical outcomes yet added treatment-related mortality with the anti-EGFR antibody cetuximab in improving outcomes for patients with locoregional anal cancer treated with chemoradiation." (PMID 36980587, 2023). "Human Epidermal Growth Factor Receptor-1 (EGFR), a transmembrane tyrosine kinase receptor (RTK), has been associated with several types of cancer, including breast, lung, ovarian, and anal cancers." (PMID 30563058, 2018). "FGF17 either enhances cellular proliferation or inhibits apoptosis and EGFR induces signaling pathway in different kinds of cancer, namely, lung and anal cancer." (PMID 24967385, 2014). "The presence of epidermal growth factor receptor (EGFR) overexpression in anal carcinoma indicates a role for anti-EGFR therapies, such as cetuximab." (PMID 24944707, 2014). "We present three cases of refractory anal cancers, treated with EGFR inhibitors, after having received the recommended chemotherapy regimens." (PMID 21772841, 2011). "It remains to be seen if biomarkers of response to anti-EGFR therapies shown to be of use in other carcinoma types are applicable to anal carcinoma." (PMID 21063399, 2010). "This EGFR target lies proximally within this oncogenic MAPK signaling pathway, which has been linked to adaptive resistance to radiation in other cancer types besides anal cancer." (PMID 36980587, 2023). "Our results also suggest that the use of the anti-EGFR drug could be used in anal carcinoma, but further studies analysing the effect of this drug in relation to molecular alterations are needed." (PMID 24642661, 2014). "Cetuximab (moAb anti-EGFR) represents a promising treatment choice for anal carcinoma." (PMID 24642661, 2014). "EGFR expression in anal carcinoma is observed in approximately 80–90% of cases." (PMID 24642661, 2014). "We conclude that EGFR inhibitors may play a vital role in the treatment of anal cancer and we suggest that large trials are be conducted in order to clarify their efficacy and to improve therapeutic management." (PMID 21772841, 2011). "However, the incidence of other gene alterations, e.g. BRAF and PIK3CA mutations, involved in the response to anti-EGFR therapies in colorectal cancer has not been studied in anal carcinoma." (PMID 24642661, 2014). "Moreover, the animal model shares more biological markers that are similar to other human cancers, such as activation of EGFR and increased levels of p-Stat3 and pro-inflammation cytokines, which could provide more strategies for exploring anal cancer treatments." (PMID 24124460, 2013). "None of these studies of EGFR in anal cancer have identified a direct link between EGFR status and prognosis after chemoradiation." (PMID 21063399, 2010). "Our study shows that KRAS and BRAF are not mutated in anal carcinoma, whereas PIK3CA, mutated in about 20% of cases, may represent a mechanism of resistance to anti-EGFR treatment, such as cetuximab." (PMID 24642661, 2014).
B-cell lymphoma (15 papers, 2014 to 2025). "These are generated to bind CD16 on NK cells and one or two tumor antigens such as CD19 and CD20 (B-cell non-Hodgkin’s lymphoma), CD33 or CD33 and CD123 (AML), CD30 (Hodgkin’s lymphoma), EGFR or EpCAM (EGFR/EpCAM overexpressing carcinomas), and many others." (PMID 28405194, 2017). "The EGFR/TLR3 axis activated by TAR RNA is specific for carcinoma cells that express EGFR, since B-cell lymphoma cells that lack EGFR do not respond to the HIV-positive exosomes for proliferation." (PMID 30389917, 2018). "However, B-cell lymphoma cells, which lack EGFR, do not respond to the protumor effect of HIV+ exosomes." (PMID 32051269, 2020). "Indeed, all three B-cell lymphoma cell lines lacked EGFR expression, while they all expressed the B-cell marker CD19." (PMID 30389917, 2018).
coronary artery disease (15 papers, 2008 to 2025). "MiR-23a also regulates the vasculogenesis of coronary artery disease via targeting epidermal growth factor receptor." (PMID 31936594, 2020).
diffuse large B-cell lymphoma (15 papers, 2020 to 2023). "Moreover, EGFR overexpression was associated with drug-resistance of diffuse large B-cell lymphoma (DLBCL), the most common subtype of NHL." (PMID 33093643, 2021). "It has been reported that EGFR activation contributed to PDGFD induced-ibrutinib resistance in diffuse large B-cell lymphoma (DLBCL)." (PMID 35504024, 2022). "Compared to non-epithelial cancers, lymphoid neoplasm diffuse large B-cell lymphoma (DLBC), and uveal melanoma (UVM), all 20 epithelial cancers expressed high levels of EGFR mRNA (black for epithelial and gray for non-epithelial cancers)." (PMID 37545491, 2023).
pericardial effusion (15 papers, 2012 to 2026). Fluid collection within the pericardial sac, usually due to inflammation. "Next-generation sequencing using pericardial effusion revealed concurrent EGFR L858R mutation and MET amplification." (PMID 40028158, 2025). "In this phase 2 trial, a combination of osimertinib and bevacizumab was administered to patients with previously untreated stage IV or relapsed EGFR-mutated NSCLC complicated by malignant pleural or pericardial effusion." (PMID 36438852, 2022). "In 273 advanced NSCLC patients with EGFR mutations, 29 cases had pericardial effusion, among which 6 patients with small amount of pericardial effusion were excluded, and 23 patients were analyzed." (PMID 29357971, 2018). "Both for EGFR and KRAS the category pleural and pericardial effusions was associated with a difference in mutation frequency compared to primary tumors (EGFR OR = 2.80 (95 % CI 1.22-6.41), p = 0.015; KRAS OR = 0.35 (95 % CI 0.14–0.86), p = 0.022)." (PMID 22528563, 2012). "Particularly, the antitumor effect of this treatment on EGFR-mutated NSCLC with pleural or pericardial effusion, a condition associated with reduced efficacy of EGFR TKI monotherapy, is unknown." (PMID 36438852, 2022). "Therefore, we evaluated the efficacy and safety of osimertinib plus bevacizumab in patients with EGFR-mutated NSCLC complicated with malignant pleural or pericardial effusion (MPE) for whom combination therapy may be particularly effective." (PMID 36438852, 2022). "Pericardial effusion and lower serum potassium levels were independent predictors of additional QTc prolongation after sequential EGFR-TKI treatment." (PMID 38774407, 2024). "After adjusting for confounding factors, pericardial effusion and lower serum potassium levels were independent predictors of additional QTc prolongation during sequential third-generation EGFR-TKI treatment." (PMID 38774407, 2024). "A single arm phase II trial of osimertinib combined with bevacizumab for patients with EGFR-mutated NSCLC and malignant pleural and/or pericardial effusion is ongoing." (PMID 35650550, 2022). "We found an increased EGFR mutation frequency (27 %) and a decreased KRAS mutation frequency (19 %) in patients with malignant pleural or pericardial effusions." (PMID 22528563, 2012). "In conclusion, our study did not meet its primary end point; compared with osimertinib monotherapy, osimertinib and bevacizumab combination treatment failed to increase the 1-year PFS of patients with EGFR-mutated advanced NSCLC with malignant pleural or pericardial effusion." (PMID 36438852, 2022). "Among the 3 actionable alterations with SNVs/indels, 2 (66.7%) (EGFR L861Q and KRAS G12C) had a higher VAF in pericardial effusion compared with PE-cfDNA." (PMID 35646096, 2022). "Meanwhile, EGFR L858R and MET amplification remained a modest consistence (40–80%) between paired pericardial effusion-cfDNA and pericardial effusion-sDNA." (PMID 35646096, 2022). "Therefore, we prospectively evaluated the efficacy and safety of osimertinib and bevacizumab cotreatment in patients with EGFR-mutated advanced NSCLC with pleural or pericardial effusion who had not previously received systemic chemotherapy for advanced disease." (PMID 36438852, 2022). "During EGFR-TKI treatment, oncologists should pay close attention to patients’ top-QTc interval variation, especially when combined with pericardial effusion and lower serum potassium level, which were independent risk factors for additional QTc prolongation after sequential EGFR-TKI treatment." (PMID 38774407, 2024). "Among them, EGFR T790M, EGFR E746_A750delELREA, EGFR L861Q, KRAS G12C, EML4-ALK (exon 18: exon 20) fusion, EML4-ALK (exon 20: exon 20) fusion, and ERBB2 Y772_A755dupYVMA were detected in both pericardial effusion-cfDNA and pericardial effusion-sDNA." (PMID 35646096, 2022).
pericardial effusion (continued). "Among the actionable alterations, MET amplification exhibited the highest population frequency, while EGFR E746_A750delELREA, EGFR T790M, EML4-ALK (exon 20: exon 20) fusion, and KRAS G12C displayed a 100% consistency between the tumor tissue and pericardial effusions." (PMID 35646096, 2022). "Interestingly, two studies that reported the efficacy of erlotinib and bevacizumab conducted exploratory subanalyses of patients with and without pleural or pericardial effusions, factors that predict poor efficacy of first- and second-generation EGFR TKIs." (PMID 36438852, 2022). "Moreover, we identified EGFR L861Q and MET amplification as two unique actionable alterations in pericardial effusion, suggesting that NGS sequencing on pericardial effusion could lead to identification of advanced NSCLC patients who are qualified for TKI based therapy." (PMID 35646096, 2022).
systemic lupus erythematosus (15 papers, 2014 to 2025). An autoimmune multi-organ disease typically associated with vasculopathy and autoantibody production. "That anti-IFNAR reduction of photosensitive responses across two lupus models depended on EGFR signaling and LC ADAM17 provided strong support for the idea that IFN-I contributes to photosensitivity at least in part by promoting LC ADAM17 sheddase dysfunction." (PMID 38860651, 2024). "Most abundantly predicted compounds include anti-cancer drugs targeting tubulin polymerization, MAPK signaling, and EGFR signaling, as well as current lupus standard-of-care therapies, including corticosteroids and prostaglandin synthesis inhibitors." (PMID 33060686, 2020). "Based on its role in regulating EGFR, we hypothesized that PXK participates in BCR internalization and lupus-associated variants in the PXK locus differentially regulate BCR internalization." (PMID 25620976, 2014). "After treatment with erlotinib, a first-generation EGFR TKI, 1 patient experienced fever, erythematous patches, and butterfly-shaped erythema over the cheeks consistent with a systemic lupus erythematosus-like reaction." (PMID 39430640, 2024). "While PXK is involved in trafficking of epidermal growth factor Receptor (EGFR) in COS-7 cells, mechanisms linking PXK to lupus pathophysiology have remained undefined." (PMID 25620976, 2014). "We have previously shown that Langerhans cells (LCs) limit keratinocyte apoptosis and photosensitivity via a disintegrin and metalloprotease 17 (ADAM17)-mediated release of epidermal growth factor receptor (EGFR) ligands and that LC ADAM17 sheddase activity is reduced in lupus." (PMID 38860651, 2024). "Likewise, EGFR, YTHDF2 also regulate the MAPK and NF-kB signalling in systemic lupus erythematosus (SLE)." (PMID 34833061, 2021).
type 1 diabetes (15 papers, 2012 to 2025). "It is reported that enhanced EGFR phosphorylation and its downstream ER stress are involved in cardiac fibrosis and vascular endothelial dysfunction in type I diabetes mellitus." (PMID 35990823, 2022). "Further, in a model of type 1 diabetes, the effect of acute activation or chronic inhibition of EGFR and ErbB2 signaling on heart function was also studied." (PMID 34408653, 2021). "Isolated heart perfusion model of global ischemia was used to study the effect of chronic inhibition or acute activation of EGFR/erbB2 signaling on cardiac function in a rat model of type-1 diabetes." (PMID 22720029, 2012). "In a rat model of type 1 diabetes, chronic in vivo administration of a specific pharmacological inhibitor of EGFR abrogated the cardiac benefits of preconditioning implying a critical role of EGFR/ErbB1 in cardiac preconditioning." (PMID 34408653, 2021). "In vivo study has showed that EGFR inhibitor AG1478 can attenuate renal oxidative stress and renal injury in mouse model with type 1 diabetes." (PMID 28427241, 2017).